SLC44A4 (solute carrier family 44 member 4)
Description:
Choline transporter that plays a role in the choline-acetylcholine system and is required to the efferent innervation of hair cells in the olivocochlear bundle for the maintenance of physiological function of outer hair cells and the protection of hair cells from acoustic injury (By similarity). Also described as a thiamine pyrophosphate transporter in colon, may mediate the absorption of microbiota-generated thiamine pyrophosphate and contribute to host thiamine (vitamin B1) homeostasis. [Isoform 3]: Also has thiamine pyrophosphate transporter activity.
Synonyms: hTPPT1; C6orf29; CTL4; NG22; FLJ14491; TPPT; DFNA72
Tractability: Antibody: UniProt places it where antibodies can reach, with high confidence; its Gene Ontology location is reachable by antibodies, with high confidence; UniProt predicts a signal peptide or a membrane-spanning region. Other modalities: a drug acting on it is in phase 1 trials.
Target class: Transporter
Gene: Protein-coding gene on chromosome 6 (31,863,192 to 31,879,198, reverse strand). Ensembl gene ENSG00000204385.
Subcellular location: Membrane; Apical cell membrane
Pathways (Reactome):
Metabolism: Synthesis of PC
Transport of small molecules: SLC-mediated bile acid transport
Gene Ontology:
Molecular function: choline transmembrane transporter activity; thiamine pyrophosphate transmembrane transporter activity; transmembrane transporter activity
Biological process: acetylcholine biosynthetic process; acetylcholine secretion; choline transport; positive regulation of cell growth; thiamine pyrophosphate transmembrane transport; bile acid and bile salt transport; neuromast hair cell development; otolith formation; phosphatidylcholine biosynthetic process; transmembrane transport
Cellular component: apical plasma membrane; extracellular exosome; membrane; plasma membrane
Genetic constraint (gnomAD): Loss-of-function variants: 75 observed, 100.57 expected, observed/expected ratio (o/e) 0.75, 90% interval 0.62 to 0.9. The upper end of that interval is the gene's LOEUF score, 0.9, which puts it in group 3 of 6, group 1 being the genes least tolerant of losing a copy. Missense variants: 799 observed, 931.76 expected, observed/expected ratio (o/e) 0.86, 90% interval 0.81 to 0.91. Synonymous variants: 325 observed, 376.61 expected, observed/expected ratio (o/e) 0.86, 90% interval 0.79 to 0.95.
Gene-disease validity (ClinGen):
ClinGen rates the evidence that SLC44A4 causes each of these diseases.
nonsyndromic genetic hearing loss (autosomal dominant): Limited. A disease characterized by hearing loss that is not part of a larger syndrome.
Homologues: Orthologues: chimpanzee SLC44A4 (99% identical), macaque SLC44A4 (97% identical), pig SLC44A4 (85% identical), dog SLC44A4 (83% identical), mouse Slc44a4 (82% identical), rat Slc44a4 (82% identical), guinea pig SLC44A4 (81% identical), rabbit SLC44A4 (74% identical), tropical clawed frog slc44a4 (61% identical), zebrafish slc44a4 (49% identical). Paralogues in human: SLC44A2 (52% identical), SLC44A5 (47% identical), SLC44A1 (25% identical), SLC44A3 (24% identical).
Diseases named in the same sentence as SLC44A4 in open-access papers:
SLC44A4 is named in the same sentence as 65 diseases in open-access papers, as found by Europe PMC text mining. Sharing a sentence is not in itself a finding about the gene and the disease. The quoted sentences say what the papers report.
breast carcinoma (6 papers, 2020 to 2024). "Other selected genes, SLC40A1, ADAMTS15, THSD4, GREB1, and SLC44A4 have been reported to be related to breast cancer, and ZG16B, FDCSP, and SRARP have been associated with other types of tumors." (PMID 32795265, 2020). "Genes identified in breast cancer included ERBB3, LIV‐1 and SLC44A4; in colorectal cancer CD71, PTK7 and SLC44A4; in lung cancer SLC44A4; in prostate cancer LIV‐1 and PSMA; and finally in stomach cancer CD71 and CD74." (PMID 37740463, 2023). "A similar result was obtained when using a six-gene (AGR2, SLC44A4, TBC1D9, FOXA1, GATA3, and CA12) breast cancer steroid response module (Kruskal-Wallis p = 0.01 across all patients, p = 0.94 in HRDetect-high patients, and p = 0.02 in HRDetect-low/intermediate patients)." (PMID 33568222, 2021). "Thus, ADCs directed against SLC44A4 could potentially be evaluated in breast cancer; CD71, PTK7 and SLC44A4 in colorectal cancer; SLC44A4 in lung cancer; LIV‐1 in prostate cancer, and finally CD71 and CD74 in gastric cancer." (PMID 37740463, 2023).
colon cancer (3 papers, 2016 to 2023). "In addition, PTK7 and SLC44A4 showed high expression in breast and colon tumours." (PMID 37740463, 2023).
migraine (3 papers, 2022 to 2026). "Among the shared genes, four genes (NEU2, SLC44A4, and EHMT2 on chromosome 6, and STAC3 on chromosome 12) were associated with both migraine and headache." (PMID 36808568, 2023). "Cross-trait gene-based overlap analysis identified 33 genes significantly associated (Pgene-based < 3.85 × 10−6) with migraine and T2D, and 11 genes associated with headache and T2D, with 7 genes (EHMT2, SLC44A4, PLEKHA1, CFDP1, TMEM170A, CHST6, and BCAR1) common between them." (PMID 36292730, 2022). "We delve into the specific shared risk loci, such as TRIM32 and SLC44A4, and demonstrate how they converge on dysregulated biological pathways, notably IL-1, TNF-α, and MAPK/ERK signaling that drive both peripheral inflammation in endometriosis and neuroinflammation in migraine." (PMID 42222530, 2026). "Among these shared genome-wide significant genes between migraine, headache, and glycemic traits, four (NEU2, SLC44A4, EHMT2, and STAC3) were common to both migraine and headache that overlapped more than one glycemic trait." (PMID 36808568, 2023). "Notably, seven of these genes (EHMT2, SLC44A4, PLEKHA1, CFDP1, TMEM170A, CHST6, and BCAR1) were genome-wide significant for all three traits (migraine, headache, and T2D)." (PMID 36292730, 2022).
pancreatic cancers (3 papers, 2021 to 2024). "SLC44A4 (CTL4) is a protein differentially expressed in prostate and pancreatic cancers with low expression in normal tissues." (PMID 33917882, 2021). "In an effort to identify crucial biomarkers for pancreatic cancer prognosis, a study discovered a total of four genes, ACSL5, SLC44A4, LOX, and TOX3, showing correlation with PFS as indicated by qPCR and immunohistochemical staining." (PMID 39108264, 2024).
renal cell carcinoma (3 papers, 2021 to 2023). "Previous studies highlighted the involvement of DNA methylation in the regulation of the SLC44A4 and SLC34A2 in colon adenocarcinoma, renal cell carcinoma, small-cell lung cancer, and papillary thyroid carcinoma." (PMID 37397501, 2023).
colorectal cancer (2 papers, 2023). A primary or metastatic malignant neoplasm that affects the colon or rectum. "SLC44A4 (solute carrier family 44 member 4) is a membrane transporter that is primarily expressed in the pancreas, liver, and small intestines and that has been linked to lung, prostate, and colorectal cancers." (PMID 38090559, 2023).
gastric cancer (2 papers, 2023 to 2024). A primary or metastatic malignant neoplasm involving the stomach. "For instance, agents against some overexpressed targets such as CD71, PTK7, CD74 and SLC44A4 could be evaluated in some conditions such as breast, colon and gastric cancer." (PMID 37740463, 2023). "We also identified that ADCs against CD71, PTK7, CD74, SLC44A4 and LIV‐1 were not under evaluation in breast, colorectal, prostate and gastric cancer, which suggests potential opportunities for evaluation." (PMID 37740463, 2023).
Atrophy (1 paper, 2011). Any weakening or degeneration, especially through lack of use. "Two highly up-regulated genes, SLC44A4 and PLAT, could be associated with the symptoms of vaginal dryness and atrophy." (PMID 22073175, 2011).
clear cell renal cell carcinoma (1 paper, 2022). "The latest research indicates that SLC44A4 may be a potential target for the diagnosis, prognosis, and treatment of clear cell renal cell carcinoma." (PMID 35872794, 2022).
kidney cancer (1 paper, 2020). Primary or metastatic malignant neoplasm involving the kidney. "In kidney cancer, SLC22A6, SLC22A7, SLC22A13, SLC25A4, SLC34A1, and SLC44A4 were significantly downregulated." (PMID 32461965, 2020).
renal papillary cell carcinoma (1 paper, 2020). "PDZK1, SLC22A2, and SLC44A4 have also a prognostic value for patients with renal papillary cell carcinoma." (PMID 32599841, 2020).
rheumatoid arthritis (1 paper, 2021). A chronic, systemic autoimmune disorder characterized by inflammation in the synovial membranes and articular surfaces. "Most significant phenotypes were observed for SLC44A4 with rheumatoid arthritis (p = 1.51 × 10–105) and white blood cell (p = 6.16 × 10–105)." (PMID 34512723, 2021).
schizophrenia (1 paper, 2020). A major psychotic disorder characterized by abnormalities in the perception or expression of reality. "Of interest is the DMR located in exon 10 of the SLC44A4 gene; a gene recently implicated in a study looking at the role of the major histocompatibility complex region in schizophrenia susceptibility." (PMID 32075955, 2020).
sialidosis (1 paper, 2015). "Defects in SLC44A4 have been linked to sialidosis, which presents with a spectrum of symptoms including eye abnormalities." (PMID 25629512, 2015).
ulcerative colitis (1 paper, 2021). An inflammatory bowel disease involving the mucosal surface of the large intestine and rectum. "The SLC44A4 gene was reported to be associated with ulcerative colitis (UC) susceptibility in the Indian, Japanese, and Chinese populations." (PMID 34367251, 2021).
tumor (30 papers, 2015 to 2026). "An ADC comprising anti-SLC44A4 antibody conjugated to MMAE by a VC linker (ASG-5ME) controlled tumor growth in multiple tumor models, including subcutaneous and orthotopic PDX models of pancreatic cancer." (PMID 37880707, 2023). "Among the highest dysregulated SLCs, SLC44A4 was upregulated in 17 of 33 tumor types when compared to pooled GTEx control group, including the tumors of gastrointestinal origin." (PMID 37397501, 2023). "Based on these results, we hypothesize that the SLC44A4, uniquely expressed in tumour cells metastasizing to the leptomeninges, could serve as a potential therapeutic target for SCLC leptomeningeal metastasis." (PMID 38644473, 2024). "This was expected as oncogene-enriched subtype tumours exhibited more aggressive tumour growth and had an increased expression of gene mutations involved in cell proliferation (ERBB2, SLC44A4, EPCAM, CLDN3, and CLDN4), cell differentiation (ELF3 and GPX2), and mucin production (KRT20)." (PMID 36723696, 2023). "Similarly, to SLC44A4, the upregulation of SLC52A3 was observed in more than half of TCGA tumor types when compared to pooled GTEx control group." (PMID 37397501, 2023). "In contrast, DPEP1, HADH, PLIN2, SCD5, SLC44A4, and UGT8 may function to suppress tumor growth via the regulation of immune cells with antitumor activity such as resting memory CD4 T cells, resting NK cells, M2 macrophages, resting and activated DCs, and resting mast cells." (PMID 38090559, 2023). "Concomitantly, the last CG probesets of SLC44A4 body region (from cg25560247 to cg20383155) and the 3′UTR CG probeset showed a cluster of positive correlated pairs (r ≥ 0.4; p ≤ 0.05), especially for CESC, COAD, DLBC, ESCA, KIRP, PAAD, and READ (≥10 GC probesets per tumor type)." (PMID 37397501, 2023).
cancer (23 papers, 2014 to 2025). A tumor composed of atypical neoplastic, often pleomorphic cells that invade other tissues. "Among the various cancers examined, SLC22A6, SLC22A7, SLC22A13, SLC25A4, and SLC34A1 were significantly downregulated, while SLC44A4 showed different expression patterns in different cancers (upregulated or downregulated)." (PMID 32461965, 2020). "The expression levels of SLC22A6, SLC22A13, SLC25A4, SLC34A1, and SLC44A4 were significantly correlated with the clinical stage of the cancer." (PMID 32461965, 2020). "We used the Oncomine database to analyze the expression levels of SLC22A6, SLC22A7, SLC22A13, SLC25A4, SLC34A1, and SLC44A4 in various cancers and their normal tissues." (PMID 32461965, 2020). "Given published evidence on transport of ThDP by cellular membrane transporters SLC19A1 and SLC44A4, this experimental design may overcome complex regulation of ThDP synthesis in cancer cells, being more straightforward to extend the interval of intracellular ThDP content." (PMID 33868388, 2021). "In the betaine part, the expression of SLC44A4, CHDH, and BHMT was disordered across cancers and had a general downward trend." (PMID 31828117, 2019). "In cancer tissues, SLC25A4 and SLC44A4 proteins did not change significantly in terms of staining, intensity, and quantity." (PMID 32461965, 2020).
infection (11 papers, 2009 to 2024). The state of being infected such as from the introduction of a foreign agent such as serum, vaccine, antigenic substance or organism. "This indeed appeared to be the case as activity of the full-length (as well as the minimal) SLC44A4 promoter (transfected into NCM460 cells) were significantly reduced following infection with EHEC." (PMID 31639155, 2019).
GI tumor (1 paper, 2022). "All GI tumor samples except STAD showed significantly elevated expression of SLC44A4 when compared to normal tissue samples." (PMID 35970857, 2022).
SLC44A4 also shares sentences with these, for which no sentence is quoted: melanoma (9 papers); malaria (7); hypophysitis (3); E. coli infection (2); Headache (2); lymphoma (2); metastatic malignant melanoma (2); non-small cell lung carcinoma (2); type 1 diabetes mellitus (2); anemia (1); bacterial infection (1); cardiac disease (1); cervical cancer (1); cholangiocarcinoma (1); collagenous colitis (1); colon adenocarcinoma (1); endocrine disorder (1); endometriosis (1); enteritis (1); fungal infection (1); glioma (1); Granuloma (1); hematologic malignancies (1); immune dysfunction (1); leukemia (1); lung carcinoma (1); mesenchymal tumors (1); mesothelioma (1); metastasis (1); metastatic disease (1).
A further 16 diseases each share a sentence with SLC44A4 in 1 paper.